CREB3 (cAMP responsive element binding protein 3)
Diseases named in the same sentence as CREB3 in open-access papers (continued):
Sharing a sentence is not in itself a finding about the gene and the disease.
neuroblastoma (2 papers, 2023 to 2025). Neuroblastoma (NB) is the most common solid, extracranial childhood tumor. "We previously characterized the processing and degradation of CREB3 in a mouse neuroblastoma cell line, Neuro2a." (PMID 36982858, 2023). "Recently, we reported on the activation and regulation of ER stress responses and CREB3 using the mouse neuroblastoma cell line Neuro2a." (PMID 36982858, 2023). "As Neuro2A cells are used both as neurons and as a neuroblastoma model, we hypothesize that the positive regulation of CREBRF-CREB3 is a cancer-specific mechanism to promote the stability and activation of the pro-tumor CREB3." (PMID 41301006, 2025).
type 2 diabetes (2 papers, 2024). "The A allele of rs373863828 in CREB3 regulatory factor is associated with high Body Mass Index, but lower odds of type 2 diabetes." (PMID 38829901, 2024).
bladder cancers (1 paper, 2024). "Aberrant expression of CREB3 has been observed in diverse cancer types such as breast and bladder cancers, which can affect tumour progression and metastasis." (PMID 38894657, 2024).
Chlamydia infection (1 paper, 2025). "Disruption in Creb3 transcriptional regulatory mechanisms could be significantly associated with Chlamydia infection." (PMID 40786607, 2025). "Our findings that Chlamydia infection disrupts these networks, particularly through the alteration of key transcription factors like Creb3, suggest that the pathogen employs sophisticated mechanisms to dampen the host’s immune response." (PMID 40786607, 2025). "Moreover, we also discovered a significant positive correlation between Creb3 and Ido1 expression in GC cells, which is thought to possibly constrain the specific expression of Ido1 in GC cells by inhibiting Creb3 activity post-Chlamydia infection, leading to impaired GC cell barrier function." (PMID 40786607, 2025).
colon cancer (1 paper, 2024). "Notably, CREB3-CF overexpression in HT-29 colon cancer cells induced the formation of budding EVs and multiple intracellular vesicles." (PMID 38480902, 2024).
dengue virus infections (1 paper, 2021). "CREB3 (cyclic AMP-responsive element-binding protein 3), which enhances the transcription of genes involved in secretory pathways, takes part in the cellular response to Zika and dengue virus infections." (PMID 33807814, 2021).
helminth infection (1 paper, 2022). "CREB3 was a high-degree node, differentially associated with 27 other genes, and it showed mostly positive z-scores, thus, its expression was correlated in the unstimulated samples but those correlations were lost upon stimulation by helminth infection and paratuberculosis." (PMID 36482891, 2022).
Hyperinsulinemia (1 paper, 2024). An increased concentration of insulin in the blood. "It is worth noting that CREB3 probably suppresses INSR signaling by binding to intracellular domain of INSR‐A and INSR‐B, which provides novel insight for therapy of HCC patients with hyperinsulinemia." (PMID 38952575, 2024).
Obesity (1 paper, 2022). Accumulation of substantial excess body fat. "For example, CREB3, STAT1, and STAT3 are important regulators of glucose and lipid metabolism in models of high-fat diet and obesity." (PMID 36389068, 2022).
ocular infection (1 paper, 2026). "In addition, PBA is also a well-known endoplasmic reticulum stress inhibitor and has been shown to modulate CREB3 pathways in HSV-induced ocular infection, suppress viral replication, and associated inflammation." (PMID 41358724, 2026).
Sepsis (1 paper, 2025). Sepsis is defined as life-threatening organ dysfunction caused by a dysregulated host response to infection. "The levels of CLU, BCL2L1, USP14, PTPN1, OPA1, and CREB3 were elevated during sepsis and demonstrated a positive correlation with sepsis score." (PMID 40867920, 2025).
thyroid cancer (1 paper, 2021). "In summary, CREB3 activated ZFAS1 drives the metastasis of thyroid carcinoma, which is involved in the miR-373-3p/MMP3 regulatory axis." (PMID 34249125, 2021). "Using the online prediction tool, CREB3 was predicted as the transcription factor (TF) of ZFAS1 that contained two binding sites on its promoter region, and CREB3 was positively correlated with ZFAS1 in thyroid carcinoma cohorts." (PMID 34249125, 2021).
tumor (25 papers, 2017 to 2025). "The expression levels of CREB3 were higher in the tumor tissues, and higher expression levels were associated with a poorer HCC OS." (PMID 38151984, 2023). "TACE-induced tumor localized ischemia and hypoxia trigger CREB3 activation, subsequently upregulating M17 module (stemness/metastasis) gene expression, enabling scPAS + cells to tolerate treatment-induced damage while maintaining tumor progression capacity." (PMID 41450464, 2025). "Our findings revealed that the TFs E2F1, HMGA1, MYC, FOSL1 and CREB3 exhibited exceptional levels of activity within C2 UBE2C+ tumour cells." (PMID 38894657, 2024). "Quantitative real‐time PCR (qRT‐PCR) analysis demonstrated that the mRNA levels of CREB3 were decreased in tumor tissues compared with corresponding peritumoral tissues." (PMID 38952575, 2024). "IHC analysis of subcutaneous tumor and lung metastasis tissues also revealed that CREB3 expression was inversely correlated with phosphorylation of IRS1 and AKT." (PMID 38952575, 2024). "Operating as a pivotal sensor of endoplasmic reticulum stress, CREB3 assumes an indispensable role in the viability of tumour cells when confronted with such stressors." (PMID 38894657, 2024). "In conclusion, CREB3 acted as a tumor suppressor in HCC, which inhibited AKT phosphorylation through independently interfering interaction of INSR with IRS1, and transcriptionally activating RBM38." (PMID 38952575, 2024). "Subsequently, we substantiated the influence of CREB3 on the migratory and invasive abilities of tumour cells through scratch and transwell experiments." (PMID 38894657, 2024). "While CREBRF suppresses tumor progression by downregulating CREB3 and ATG5, NR3C2 inhibits cancer cell survival and migration through repression of β-catenin and c-Myc." (PMID 36358691, 2022). "For the first time, we identified that miR124-3p and miR766-3p attenuate expression of CREBRF and NR3C2, respectively, in HNSCC, which promotes aggressive tumor behavior by inducing the signaling axes CREB3/ATG5 and β-catenin/c-Myc." (PMID 36358691, 2022). "The overexpression of CREB3 promoted the proliferation and invasion of SHG-44 cells, while the downregulation of CREB3 inhibited the tumor growth and invasion of U251MG cells." (PMID 31612863, 2019). "In the present study, the results of RNA sequencing indicated that cAMP responsive element binding protein 3 (CREB3) was upregulated in tumor tissues from patients with GBM." (PMID 31612863, 2019). "CREB3 expression correlated with clinicopathological parameters such as the tumor volume, KI67 expression, distant metastasis and World Health Organization stage." (PMID 31612863, 2019). "The relative mRNA levels of CREB3 were notably lower in CREB3-shRNA2-transfected tumor tissues than in NC-transfected tissues." (PMID 31612863, 2019). "The data indicated that knockdown of CREB3 significantly upregulated the protein levels of Bax and active caspase 3 in tumor tissues." (PMID 31612863, 2019). "CREB3L3 and CREB3L4 are novel homologs of CREB3 with conflicting pro- and anti-tumor roles." (PMID 41301006, 2025). "Tumorigenicity assays in nude mice indicated that tumor growth induced by CREB3 knockdown could be partly rescued by decreased INSR expression or enhanced RBM38 expression." (PMID 38952575, 2024). "In our study, we summarized that CREB3 affected signaling pathway through two methods, including interaction with receptor and transactivation of downstream genes, which had independent effect on progression of tumor." (PMID 38952575, 2024). "In the present study, we revealed CREB3 as a novel tumor suppressor in HCC." (PMID 38952575, 2024). "In contrast, overexpression of CREB3 remarkably decreased the tumor weight and volume of HLF cells." (PMID 38952575, 2024). "Moreover, the CCK‐8 assay exhibited a notable decrease in tumour cell viability within the CREB3 knockdown group when compared to the control group." (PMID 38894657, 2024).
tumor (continued). "In addition, effects of CREB3 on RBM38 was verified by IHC staining in mice tumor slices with CREB3 overexpression or knockdown." (PMID 38952575, 2024). "Also, circTADA2A improved CREB3 expression to enhance OS progression and metastasis by sponging miR-203a-3p and functioned as a tumor promoter in OS." (PMID 33817236, 2020). "As expected, CREB3 knockdown significantly inhibited tumor growth." (PMID 30940151, 2019). "We demonstrated that CREB3 could bind to the promoter of c-Jun and subsequently enhance the expression of mmp9, an important biomarker for tumor metastasis, and Bcl-2, a pivotal antiapoptotic molecule in the plasma." (PMID 30940151, 2019). "CircTADA2A functions as a tumor promoter in OS to increase malignant tumor behavior through the miR-203a-3p/CREB3 axis, which could be a novel target for OS therapy." (PMID 30940151, 2019). "This evidence supports the notion that CREB3 functions as a tumor promoter." (PMID 31612863, 2019). "The downregulation of CREB3 significantly repressed xenograft tumor growth." (PMID 31612863, 2019). "The tumor weights were markedly lower in the CREB3-shRNA2 group than in the NC group." (PMID 31612863, 2019). "However, some evidence suggests that CREB3 has anti-tumor properties." (PMID 41301006, 2025). "Although the ranking order may vary, the majority of the top-ranked TEff/EM regulons such as Rora, Fosl2, Creb3, Maf, Prdm1, Nfil3, and Nfkb1 were also identified as top-ranked regulons for active TRMs in the tumor and distant mammary mucosa." (PMID 33979626, 2021). "CREB3 plays a role in the ER‐stress induced unfolded protein response (UPR) and is a multifunctional cellular factor implicated in a number of biological processes including cell proliferation and migration, tumor suppression, and immune‐related gene expression." (PMID 30653278, 2019). "Furthermore, miR-203a-3p inhibition or CREB3 overexpression could reverse the circTADA2A silencing-induced impairment of malignant tumor behavior." (PMID 30940151, 2019). "Meanwhile, knockdown of the transcription factor CREB3, which is highly active in UBE2C+ tumour cells, significantly impedes the proliferation, migration and invasion of GC cells." (PMID 38894657, 2024). "Also, IF staining revealed that CREB3 overexpression decreased IRS1 colocalization with INSR in HLF cells and LM3 cells, as well as in HLF subcutaneous tumor tissues." (PMID 38952575, 2024). "While CREB3 functions as a transcription factor that regulates numerous genes in the central nervous system and responds to the Golgi stress, the whole CREB family is considered often overexpressed and functions as a tumor mediator in multiple cancers." (PMID 38151984, 2023). "Hence, our endeavour revolves around corroborating whether the remarkably potent transcription factor, CREB3, within UBE2U+ tumour cells, exerts regulatory control over the unrestrained proliferation of GC cells." (PMID 38894657, 2024). "In addition, HCC tissues of patients with higher alpha fetoprotein (AFP) level (>20 μg/L), incomplete tumor encapsulation, poorer differentiation grade (III and IV), earlier recurrence (<2 years), multiple tumor numbers, and satellite nodules showed lower CREB3 staining intensity." (PMID 38952575, 2024). "In contrast to responders, CREB3/ATG and β-catenin/c-Myc expression was high in non-responder tumor cells, which was associated with increased invasion of cancer cells into blood vessels and surrounding normal tissue (red arrow), indicating aggressive behavior of resistant cancer cells." (PMID 36358691, 2022).
cancer (18 papers, 2014 to 2025). A tumor composed of atypical neoplastic, often pleomorphic cells that invade other tissues. "Different cancers have taken advantage of CREB3 and its homologs to promote their survival and metastasis." (PMID 41301006, 2025). "The expression of biochemical markers involved in cellular senescence, including p21, was dramatically increased in CREB3-CF-overexpressing cancer cells." (PMID 38480902, 2024). "This dysregulation leads to the production and accumulation of CREB3-CF, which promotes karyoptotic cell death in cancer cells and suppresses their proliferation through cellular senescence." (PMID 38480902, 2024). "Proteomic studies revealed that CREB3-CF overexpression induces a DNA damage response akin to that caused by UVB irradiation, which is associated with cellular senescence in cancer cells." (PMID 38480902, 2024). "For example, circTADA2A is highly expressed in both OS tissue and cell lines, and facilitates the malignant biological behaviors of cancer cells through monitoring miR-203a-3p/CREB3 axis." (PMID 34905503, 2021). "This highlights the possibility that abrogating glycosylation may offer an alternative therapeutic strategy, which interrupts ER stress responses via CREB3 inhibition to inhibit cancer survival." (PMID 41301006, 2025). "CREB3 was reported to have effects on progression of several cancers." (PMID 38952575, 2024). "Nevertheless, the role of CREB3 in cancer formation and progression is complicated." (PMID 38952575, 2024). "Overall, the DNA loops from the reconstructed genome structure contained bioprocesses involved in transcription, such as the pre-transcriptional initiation complex and RNA polymerase II initiation complex, and transcription factors involved in cancer, such as Foxm1 and CREB3." (PMID 34828279, 2021). "Also, circNASP promoted key OS phenotypes by targeting miR-1253/FOXF1 signaling and circTADA2A promoted cancer phenotypes in OS by sponging miR-203a-3p and modulating CREB3." (PMID 34716285, 2021). "Although the present study revealed only UVB and ER suppressors as extrinsic triggering stimuli, the findings imply that the regulatory mechanism of proteases that produce CREB3-CF through CREB3-FL cleavage could be harnessed to induce karyoptosis for cancer treatment." (PMID 38480902, 2024). "The results imply that focusing on CREB3 could be a potential cancer treatment strategy." (PMID 38480902, 2024). "miR124-3p affects the CREBRF-ATG5/CREB3 axis, while miR766-3p affects the NR3C2-c-Myc/β-catenin axis; therefore, the combined targeting of these two miRNAs complement each other and shows an additive effect on sensitizing cancer cells to chemo-radiotherapy." (PMID 36358691, 2022). "CREB3 induces GBM cell proliferation and invasion by inhibiting apoptosis via downregulating proapoptotic proteins—Bax, active caspase 3, p-PERK, p-eIF2α, and ATF4, suggesting that CREB3 might inhibit anti-cancer drug-induced apoptosis." (PMID 36358691, 2022).
infection (10 papers, 2013 to 2025). The state of being infected such as from the introduction of a foreign agent such as serum, vaccine, antigenic substance or organism. "Ranked regulon activity analysis of key TFs during early infection further confirmed the predominant contributions of BATF3, MAF, and CREB3 within AntiviralMac and SusceptibleMac populations." (PMID 40723441, 2025). "Examination of these differentially expressed TFs in the three groups of GC cells showed that downregulated TFs had more pronounced changes in AUC activity post-infection, particularly Creb3." (PMID 40786607, 2025). "Although there was a notable decrease in CREB3 protein at 24-hours post-AIV infection at both 1 MOI and 10 MOI." (PMID 39652582, 2024). "With the ties of HSV-1 to the UPR, which it disarms in order to continue producing its own proteins, HSV-1 has long been suspected to modulate CREB3 during infection." (PMID 35746643, 2022). "While the expression at 0 h in both HPSE wild-type and knockout cell types was very low, CREB3 expression increased immediately post infection in both cell types." (PMID 35746643, 2022). "CREB3-transfected HCE cells showed significantly higher export of HPSE upon infection than wild-type cells." (PMID 35746643, 2022). "Western blotting analysis revealed that infection with HSV-1 triggered an increase in the expression of CREB3 after infection in both the cell types." (PMID 36298711, 2022). "The Creb3 transcription factor family appears to have a unique regulatory role that links cellular secretory capacity with development, nutritional state, infection, and other stresses." (PMID 31293620, 2019). "In agreement with the function of CrebA and CREB3 proteins described in the literature, our study finds that CrebA regulates a rapid, infection-induced increase in the expression of secretory pathway genes in the fat body, an organ analogous to the liver and adipose tissues of mammals." (PMID 29394281, 2018). "This can be determined by staining cells at different times post infection for COPII proteins, viral proteins, and CREB3." (PMID 35746643, 2022). "Cells depleted of ARF4 or CREB3 contain increased levels of ARF1, 3, and 5, and are more resistant to infection with Chlamydia and Shigella." (PMID 26594142, 2015). "However, the blots revealed a marked decrease in the relative expression of CREB3 and the unfolded protein response (UPR) regulator, GRP78, in HPSE knockout cells compared to wild-type cells at 3, 6, 9, 12, and 24 h post-infection." (PMID 35746643, 2022). "Another signaling pathway recently identified that may impact Golgi stress due to pathogen infection involves ADP-ribosylation factor (ARF)-4 and the transcription factor CREB3." (PMID 26594142, 2015). "CREB3 KD cells have increased bacterial load after infection which can be partially rescued by WT but not HY SIRT2, suggesting that regulation of SIRT2 is a key function for CREB3 during Shigella infection." (PMID 35918380, 2022).
metabolic disease (1 paper, 2019). A congenital disorder (due to inherited enzyme abnormality) or acquired (due to failure of a metabolically important organ) disorder resulting from an abnormal metabolic process. "Although Creb3L3 regulation is the best studied in response to nutrition and metabolic disease, studies of other family members, such as Creb3 and Creb3L4, suggest that they also have roles in responding to nutrient status." (PMID 31293620, 2019).
CREB3 also shares sentences with these, for which no sentence is quoted: depression (3 papers); Wilms tumor (3); aniridia (2); gastric cancer (2); mental Retardation (2); pancreatic cancer (2); WAGR syndrome (2); acute myeloid leukemia (1); Alzheimer disease (1); anaplastic large cell lymphoma (1); bone disorder (1); bone fracture (1); bone marrow failure (1); breast tumors (1); chromosomal instability syndrome (1); colorectal cancer (1); Fanconi anemia complementation group G (1); fetal growth restriction (1); Hodgkins lymphoma (1); Huntington disease (1); liver cancer (1); lung carcinoma (1); myxoid liposarcoma (1); osteoporosis (1); ovarian carcinoma (1); Papillary Thyroid Carcinoma (1); poliovirus infection (1); proliferative diabetic retinopathy (1); schizophrenia (1); Sjögren’s syndrome (1).
A further 1 disease shares a sentence with CREB3 in 1 paper.